MSS51 (MSS51 mitochondrial translational activator)
Synonyms: ZMYND17; FLJ39565
Tractability: No criterion of Open Targets' tractability assessment is met for any kind of drug.
Gene: Protein-coding gene on chromosome 10 (73,423,579 to 73,433,561, reverse strand). Ensembl gene ENSG00000166343.
Subcellular location (Human Protein Atlas): Vesicles; Cytosol
Gene Ontology:
Molecular function: protein binding
Genetic constraint (gnomAD): Loss-of-function variants: 33 observed, 40.04 expected, observed/expected ratio (o/e) 0.82, 90% interval 0.62 to 1.1. The synonymous counts are far from expectation, so gnomAD's model fits this gene poorly and the ratio says little. Missense variants: 512 observed, 592.21 expected, observed/expected ratio (o/e) 0.86, 90% interval 0.8 to 0.93. Synonymous variants: 178 observed, 225.73 expected, observed/expected ratio (o/e) 0.79, 90% interval 0.7 to 0.89.
Homologues: Orthologues: chimpanzee MSS51 (99% identical), macaque MSS51 (97% identical), dog MSS51 (85% identical), pig MSS51 (84% identical), guinea pig MSS51 (78% identical), mouse Mss51 (77% identical), rat Mss51 (76% identical), tropical clawed frog mss51 (45% identical), zebrafish mss51 (38% identical), Drosophila melanogaster Zmynd10 (8% identical). Paralogues in human: ZMYND10 (13% identical), ZMYND19 (7% identical).
Diseases named in the same sentence as MSS51 in open-access papers:
MSS51 is named in the same sentence as 3 diseases in open-access papers, as found by Europe PMC text mining. Sharing a sentence is not in itself a finding about the gene and the disease. The quoted sentences say what the papers report.
calpainopathy (1 paper, 2021). "Considering that when the gene encoding Mss51 is deleted in mice, energy production increases and mitochondrial activity improves, researchers are investigating whether the elimination of this protein would be a suitable target in a calpainopathy model." (PMID 35366260, 2021).
type 2 diabetes (1 paper, 2024). "Notably, a recent human study demonstrated Mss51 is associated with the incidence of type 2 diabetes, indicating its adverse role in regulating the energy metabolism." (PMID 39187977, 2024). "Furthermore, a molecular docking and simulation study suggests that Mss51 could be a target for type 2 diabetes by interacting with zinc‐related natural compounds." (PMID 39187977, 2024).
MSS51 also shares sentences with these, for which no sentence is quoted: Glucose intolerance (1 paper).